HSD17B14 (hydroxysteroid 17-beta dehydrogenase 14)
Description:
Catalyzes the NAD(+)-dependent oxidation of L-fucose, yielding L-fucono-1,5-lactone, which rapidly converts spontaneously to L-fucone-1,4-lactone. Can also act on D-arabinose and L-galactose, with lower catalytic efficiency. Does not use NADPH. May be the initial enzyme of the L-fucose degradation pathway in mammals.
Synonyms: DHRS10; SDR47C1; retSDR3
Tractability: Small molecule: a structure with a bound ligand is known; a high-quality ligand is known; it has a high-quality binding pocket. PROTAC: its protein half-life has been measured; a small molecule that binds it is known.
Target class: Enzyme; Oxidoreductase
Safety:
Unwanted effects reported when the protein is acted on. In parentheses: how it was acted on, where the effect was seen, and who reports it.
Increased, Liver Steatosis (inhibition; source: AOP-Wiki)
Gene: Protein-coding gene on chromosome 19 (48,813,014 to 48,837,064, reverse strand). Ensembl gene ENSG00000087076.
Subcellular location: Cytoplasm
Pathways (Reactome):
Metabolism: Estrogen biosynthesis
Gene Ontology:
Molecular function: D-threo-aldose 1-dehydrogenase activity; identical protein binding; protein binding
Biological process: L-fucose catabolic process
Cellular component: cytoplasm; cytosol
Genetic constraint (gnomAD): Loss-of-function variants: 32 observed, 32.14 expected, observed/expected ratio (o/e) 1, 90% interval 0.75 to 1.34. The upper end of that interval is the gene's LOEUF score, 1.34, which puts it in group 5 of 6, group 1 being the genes least tolerant of losing a copy. Missense variants: 369 observed, 369.73 expected, observed/expected ratio (o/e) 1, 90% interval 0.92 to 1.09. Synonymous variants: 140 observed, 156.43 expected, observed/expected ratio (o/e) 0.89, 90% interval 0.78 to 1.03.
Homologues: Orthologues: macaque HSD17B14 (97% identical), chimpanzee HSD17B14 (85% identical), guinea pig HSD17B14 (82% identical), mouse Hsd17b14 (81% identical), rabbit HSD17B14 (79% identical), rat Hsd17b14 (74% identical), zebrafish hsd17b14 (56% identical), tropical clawed frog hsd17b14 (54% identical), Caenorhabditis elegans ZK829.1 (28% identical). Paralogues in human: HSD17B2 (26% identical), HSD17B10 (24% identical), DHRS9 (23% identical), BDH1 (23% identical), HSD11B2 (23% identical), RDH16 (22% identical), RDH11 (21% identical), SDR9C7 (21% identical), HSD17B4 (21% identical), RDH12 (21% identical), RDH5 (21% identical), HSD17B8 (20% identical), and 13 more.
Diseases named in the same sentence as HSD17B14 in open-access papers:
HSD17B14 is named in the same sentence as 12 diseases in open-access papers, as found by Europe PMC text mining. Sharing a sentence is not in itself a finding about the gene and the disease. The quoted sentences say what the papers report.
breast carcinoma (6 papers, 2012 to 2024). "We have previously demonstrated that high HSD17B14 expression, an enzyme which catalyses the conversion of E2 into E1, is associated with tumour progression and worse patient outcomes in ER+ breast cancer." (PMID 36674737, 2023). "The CNVs that disrupted RAD52 and HSD17B14 genes showed enrichment among cases with a family history of the disease and/or early disease onset, suggesting a role for these alterations in breast cancer susceptibility." (PMID 37578974, 2023). "In a previous study examining mRNA of HSD17B14 in tumours from a Swedish breast cancer material, we found high expression levels of the HSD17B14-transcript to be associated with longer disease-free survival among breast cancer patients." (PMID 22792371, 2012). "This suggests a role for RAD52 and HSD17B14 in hereditary breast cancer susceptibility." (PMID 37578974, 2023). "Meanwhile, for HSD17B14, higher expression was prognostic for poor survival in women with ER+ breast cancer." (PMID 36674737, 2023). "Based on the role of HSD17B14 in steroid metabolism, we further defined the menopausal status of HSD17B14 deletion carriers in the unselected breast cancer cohort (pre/post defined by the age at diagnosis)." (PMID 37578974, 2023). "Genome-wide investigation of rare coding region CNVs in 98 high-risk Northern Finnish breast cancer cases revealed recurrent alterations in RAD51C, RAD52 and HSD17B14 genes." (PMID 37578974, 2023). "For example, high intratumoural expression of HSD17B enzymes involved in E1 synthesis, such as HSD17B2, HSD17B10 and HSD17B14, are associated with lower OS and/or DMFS in ER+ breast cancer patients." (PMID 36674737, 2023). "Transfection of HSD17B14 in human breast cancer cells significantly decreased the levels of estradiol, and further studies have suggested a role for HSD17B14 in the local inactivation of steroid." (PMID 32194632, 2020). "Hydroxysteroid 17-beta dehydrogenase 14 (HSD17B14) has been identified as a predictive biomarker for successful breast cancer treatment with tamoxifen but its expression varies among the six tissues in the dataset." (PMID 28450890, 2017). "Our investigation revealed deletion alleles in HSD17B14 and RAD52 that showed significant enrichment in the hereditary cohort and could therefore represent novel moderate-risk alleles for breast cancer." (PMID 37578974, 2023). "Consequently, it has also been suggested that proper balance of estrogens (E1:E2 ratio), in which HSD17B14 enzyme plays a critical role, could be crucial for breast cancer growth and metastasis." (PMID 37578974, 2023). "Here, we performed whole-exome sequencing based analysis of rare CNVs in 98 hereditary breast cancer cases and identified recurrent alterations in RAD52, RAD51C and HSD17B14 genes." (PMID 37578974, 2023). "Frequency of RAD52, HSD17B14 and RAD51C CNV carriers in the studied breast cancer cases and controls." (PMID 37578974, 2023).
ovarian tumours (1 paper, 2023). "Moreover, elevated intratumoural E1 synthesis by HSD17B2, HSD17B4, HSD17B6 and HSD17B14 overexpression in primary ovarian tumours correlate with lower OS." (PMID 36674737, 2023).
polycythemia vera (1 paper, 2023). "However, two HSD17B14 CNV carriers (Her14 and sister of Uns32, confirmed as carrier) were also diagnosed with polycythemia vera." (PMID 37578974, 2023).
prostate carcinoma (1 paper, 2023). A carcinoma that arises from epithelial cells of the prostate gland. "Many of the immune response related (e.g., IRF8, JAK3, PTGER4, RELB, IFITM3) and part of the lipid metabolism related genes (e.g., NR1H4, PPARGC1B, PLIN1, HSD17B14) were identified to be adaptive which addressed their significance for prostate cancer." (PMID 36809527, 2023).
tumor (4 papers, 2012 to 2023). "In that study, which comprised patients with larger tumours with lymph node involvement, higher HSD17B14 levels were associated with improved clinical outcome." (PMID 22792371, 2012). "Of the currently identified HSD17B14 deletion carriers with available tumor data from the unselected cohort, all but one had ER-positive tumors, but the menopausal status did not significantly differ compared to the rest of the unselected cohort." (PMID 37578974, 2023). "However, elevated HSD17B14 expression has been associated with poor survival in women with ER-positive breast cancer, and a high estrone (E1):17β-estradiol (E2) ratio in postmenopausal women has been shown to drive inflammation and stimulate ER-positive breast cancer tumor growth." (PMID 37578974, 2023). "When analysing all patients receiving tamoxifen, high tumour expression of 17βHSD14 significantly lowered local recurrence rates, and the current study thus supports findings from our previous study in which HSD17B14 transcripts were analysed in a different patient group, all receiving tamoxifen." (PMID 22792371, 2012).
cancer (3 papers, 2017 to 2023). A tumor composed of atypical neoplastic, often pleomorphic cells that invade other tissues. "The evidence for HSD17B14 deletion segregating with cancer phenotype within these families remained inconclusive." (PMID 37578974, 2023). "The expression of HSD17B14 changed in more invasive cancers, there was an extensive downregulation in cancer compared to adjacent control tissue form patients with lymphovascular invasion (p = 0.0298)." (PMID 28690541, 2017). "Rs4801778-T (PLEKHA4), rs11919389-C (ZBTB11), rs13050728-C (IFNAR2), and rs10774671-A (OAS1) exhibited a positive or negative regulation in TULP2, HSD17B14, LOC285359, LOC100009676, SENP7, IFNAR2, OAS3, and OAS1 in multiple cancer types." (PMID 35082790, 2021).
HSD17B14 also shares sentences with these, for which no sentence is quoted: carotid atherosclerosis (1 paper); Hepatic steatosis (1); hypospadias (1); Insulin resistance (1); ovarian carcinoma (1); sex development disorders (1).